CENPF (centromere protein F)
Diseases named in the same sentence as CENPF in open-access papers (continued):
Sharing a sentence is not in itself a finding about the gene and the disease.
cancer (continued). "Instead, in ER+/PR+/HER2- cancer cells, due to significant suppression of CENPF-mediated transcriptional activation for CHK1 induced by ADR itself, CHK1 inhibition failed to sensitize ADR toxicity." (PMID 32210727, 2020). "We further demonstrate that due to the significant downregulation of CENPF in ER+/PR+/HER2- cancer cells, CHK1 cannot be activated to defend DDR against ADR." (PMID 32210727, 2020). "The expression of CENPF has been detected in different cancers, however its expression pattern differs among various types of cancer." (PMID 32973403, 2020). "We found that the two synergistic MRs TOP2A and CENPF have both the high magnitude of increase of expression (vs. normal tissue) and the high absolute expression level in CC compared to many other cancer types." (PMID 33023625, 2020). "Centromere protein F participates in cancer metabolism by regulating pyruvate kinase M2 phosphorylation signaling." (PMID 32266115, 2020). "From ONCOMINE analysis, CENPF mRNA expression was significantly higher in BC samples across the 14 datasets in different cancer types." (PMID 31632198, 2019). "As a transcription factor, FOXM1 has many target genes including KIF20A, CENPF, CCNB1, MYC, NIMA-related kinase 2, MMP2, MMP9, and S-phase kinase-associated protein 2 that are implicated in cancer initiation, progression, or drug resistance." (PMID 31072351, 2019). "CENPF is a member of the kinetochore family, which regulates tumoral proliferation in various cancers." (PMID 31527303, 2019). "The protein CENP-F (Centromere protein F) possess significant correlation of the expression of auto-antibodies with cancer and has been described in many studies." (PMID 26308848, 2015). "Taken together, our results suggest that coincidently amplified CDK13, GMNN, and CENPF genes can play a role as common cancer-driver genes in human cancers." (PMID 22912832, 2012). "We also found that three genes – CENPF, GMNN and CDK13 – were frequently amplified in various human cancers and were significantly associated with several pathophysiological phenotypes in HCC." (PMID 22912832, 2012). "The prevalence of CENPF upregulation raises an intriguing possibility that CENPF overexpression may be a cancer-promoting event in CRC." (PMID 39922805, 2025). "Furthermore, overexpression of CENPF has been observed in varieties of cancers, including hepatocellular, gastric, breast, and lung, indicating its oncogenic nature." (PMID 38536579, 2024). "TOP2A, CENPF, TROAP, CDC20, CDCA5, and UBE2C are all reported to be associated with cancer." (PMID 36932399, 2023). "Notably, as co-expressed genes, TOP2A, BUB1 and CENPE also interacted with the CENPF protein, the high expression of which predicted poor prognosis in cancers." (PMID 37108172, 2023). "In the heatmap of the GSEA analysis, several ZNFs were upregulated in the CENPFhigh group, which belong to the zinc finger transcription factor family and have profound impacts on cancer progression, implying a presumable connection between CENPF and these ZNFs." (PMID 37108172, 2023). "Furthermore, the immunohistochemical staining results based on the HPA database revealed a significantly high positivity of the ZWINT, RRM2, NDC80, KIF4A, CEP55, CENPU, and CENPF genes in cancer tissues compared to adjacent normal tissues." (PMID 35028418, 2022). "CENPF correlates filament-mitochondrial complex, presenting impacts on cancer progression." (PMID 35346060, 2022). "Expression changes of CENPF have been shown to correlate with the prognosis of various cancers." (PMID 33390818, 2021). "CENPF, for instance, has been related to worse outcomes and survival in several cancer types." (PMID 34316711, 2021). "Autoantibodies against CENPF have been found in patients with cancers and other diseases." (PMID 35059422, 2021).
cancer (continued). "Moreover, QSOX2 silencing in NSCLC cell lines resulted in inhibition of cancer cell proliferation, induction of apoptosis, and decreased expression of cell division-related genes (CENPF and NUSAP1) and Wnt pathway activators (PRRX2 and Nuc-β-catenin)." (PMID 34350181, 2021). "By analyzing “Bittner Multi-cancer”, a multi-cancer microarray dataset using Oncomine, we observed that TOP2A and CENPF expression was higher (Student’s t-test, P = 2E-7 and 3E-4 respectively) in CC than other 15 cancer types, confirming the RNA-seq data from TCGA and the GTEx." (PMID 33023625, 2020). "Recent studies showed that CENPF played crucial roles in the progression of human cancers." (PMID 31850052, 2019). "However, the roles of CENPF in the other cancers are less well understood and the functions of CENPF remain undefined." (PMID 31632198, 2019). "Previous studies have revealed that amplified CENPF (centromere protein F) may play a role as common cancer-driver genes in human cancers." (PMID 29100313, 2017). "Together, FOXM1 and CENPF regulate target gene expression and activation in cancer cells." (PMID 27072587, 2016). "CENPF plays a role as common cancer-driver gene in human cancer." (PMID 24905462, 2014). "The identification of the amplified genes CENPF, GMNN, and CDK13 in tumors provides new insight into the carcinogenesis process, and suggests that these genes can be used as novel cancer markers for the development of diagnostic, prognostic, and/or targeted therapies." (PMID 22912832, 2012). "Thus, CENPF likely functions as an oncogene in multiple cancers." (PMID 38536579, 2024). "Thus, CENPF serves as a putative target of cancer treatment." (PMID 35346060, 2022). "Finally, we asked the question whether the two MRs (TOP2A and CENPF) are especially significant for CC compared to other cancer types." (PMID 33023625, 2020). "Subsequently, a CAF subpopulation which highly expressed cycle-related genes (CENPF, NUSAP1, and PTTG1) was annotated as proliferative CAF (prolif CAF), consistent with previous pan-cancer research." (PMID 39703515, 2024). "In the present essay, the expression patterns and prognostic value of CENPF in ACC were investigated in clinical specimens and public cancer databases, including GEO and TCGA." (PMID 35123514, 2022). "Some of these genes (e.g. CENPF, MLKL, TFDP1, MCF2L) have a known influence on cancer, while others (e.g. NUP54, BBS1 and HTT) have been superficially studied under the tumoral context." (PMID 34316711, 2021). "In contrast to the relatively known roles of BIRC5, CENPF, and STMMN1 in malignancies, functions of APOC2 and HNRNPC genes in cancer cell are less well defined." (PMID 33828156, 2021). "The products of hub PCGs mainly function as protein binding molecule and were involved in important biological processes and signaling pathways in cancer (CDK1, MKI67, CENPF, COL4A6, DACH1, etc.)." (PMID 30026672, 2018). "By our analysis, we have identified novel regions of allelic imbalance that contain several cancer related genes such as CHD1L and S100A9 at locus 1q21.1; and CENPF and ESRRG at locus 1q32-q42." (PMID 26314549, 2015). "Collectively, these results suggest that CENPF, GMNN, and CDK13 play a role in the tumorigenesis of human cancers." (PMID 22912832, 2012). "In cancer, FOXM1 is generally considered a marker for poor prognosis in cancer survival studies, often as a co-effector with other cancer master regulators, such as CENPF in prostate cancer and MYB in lymphoma." (PMID 39858603, 2025). "miR-205-5p targets centromere protein F (CENPF), a key regulator of cancer progression." (PMID 40519684, 2025). "Notably, we also found a cluster of cells that exhibited higher expression of a set of cell cycle-related genes (CENPF, NUSAP1, PTTG1, STMN1, TOP2A, and TUBA1B), which was consistent with proliferative CAFs (pCAFs) in a previous pan-cancer study of CAFs." (PMID 37833788, 2023).
cancer (continued). "Like CENPF, CENPI is overexpressed in multiple cancers and deciphers worse prognosis." (PMID 37108172, 2023). "Gedevo alignments are also related to multiple cell cycle functions, and some of them show evidence of dysregulation in cancer (ASPM, CENPF, TOP2A, and TPX2) and the acquisition of two hallmarks of cancer: sustaining proliferative signaling and evading apoptosis." (PMID 36661515, 2023). "For example, ASPM, ECT2, AURKA, BIRC5, CENPF, and EZH2 are amplified in several cancers." (PMID 36612203, 2022). "Our results suggest the possible roles of GEN1, KRIT1, CENPF, STYK1, and Sam68/KHDRBS3 in promoting cancer cell proliferation, and these findings may provide a potential therapeutic target to control mast cell malignancy." (PMID 35884586, 2022). "As cancer cells undergo active division, perhaps the up regulation of genes like BIRC5, CENPF could be a direct consequence of active mitosis." (PMID 33828156, 2021). "Centromere protein F (CENPF) has been shown to promote oncogenesis in many cancers; however, its role in LUAD has not been illustrated." (PMID 33390818, 2021). "To explore more related to drug selection in clinical use for cancer patient, we queried CMap database using CLUE and identified potential perturbations that could reverse the over-expression signature of TOP2A, CENPF and their common regulons." (PMID 33023625, 2020). "Our results suggest that inhibition of the amplified genes, CENPF, GMNN and CDK13, might be an effective new therapeutic strategy against human cancer." (PMID 22912832, 2012). "Additionally, three cancer cell subpopulations with distinct chemosensitivity profiles were identified; Subpopulation 2, characterized by high expression of CCNA2, UBE2C, and CENPF, demonstrated significantly reduced sensitivity to methotrexate, doxorubicin, cisplatin, ifosfamide, and etoposide." (PMID 42099775, 2026). "For example, TBPT significantly suppressed a series of genes involved in DNA double-strand break repair, including LIG4, CENPF, DNAJC2, RECQL, SMC6 and BRCA2 (≥ 2-fold), which are also considered vital targets for treating cancer cells without affecting normal cells." (PMID 26986511, 2016).
congenital malformation syndrome (1 paper, 2015). "We attribute, for the first time, that mutations in the CENPF gene play a causal role in human congenital malformation syndromes." (PMID 25564561, 2015).
infection (1 paper, 2023). The state of being infected such as from the introduction of a foreign agent such as serum, vaccine, antigenic substance or organism. "Four genes (ASPM, CENPF, MKI67, and TOP2A), which are well documented as stem cell and cell proliferation markers, were overexpressed at 24 h post-infection." (PMID 37478057, 2023).
CENPF also shares sentences with these, for which no sentence is quoted: esophageal squamous cell carcinoma (6 papers); head and neck squamous cell carcinoma (5); colorectal gastrointestinal stromal tumor (3); genetic diseases (2); head and neck tumor (2); liposarcoma (2); renal carcinoma (2); triple-negative breast carcinoma (2); adenocarcinoma (1); adenoma (1); asthma (1); Barrett adenocarcinoma (1); benign tumor (1); bladder urothelial carcinoma (1); breast adenocarcinoma (1); Burkitt lymphoma (1); cardiovascular disease (1); chronic hepatitis (1); colon adenocarcinoma (1); developmental delay (1); diffuse large B-cell lymphoma (1); dilated cardiomyopathy (1); endocervical adenocarcinoma (1); Ewing sarcoma (1); gastrointestinal stromal tumor (1); head and neck cancer (1); heart disease (1); heart failure (1); Horseshoe kidney (1); Joubert syndrome (1).
A further 21 diseases each share a sentence with CENPF in 1 paper.